ADAM8 (ADAM metallopeptidase domain 8)
Diseases named in the same sentence as ADAM8 in open-access papers (continued):
Sharing a sentence is not in itself a finding about the gene and the disease.
tumor (continued). "ADAM8 has been found to cleave and remodel the ECM components of the tumor stroma, and thus could directly contribute to tumor invasiveness and metastasis." (PMID 36506313, 2022). "The authors concluded that ADAM8 is overexpressed in CRC and may promote tumour growth as well as serve as an independent biomarker for the survival of CRC patients." (PMID 35565436, 2022). "To further investigate if this trend is due to the strong heterogeneity of the GBM tissue, we explored the connection between ADAM8, MMP9, and miR-181a-5p in a pilot experiment using MR-spectroscopy guided surgery at different locations in a GBM tumor tissue sample of one selected patient." (PMID 35371977, 2022). "Furthermore, there are a number of ADAM proteases lacking phenotypes in knockout mice but with a possible role in different tumor entities and specifically in PDAC, which applies for ADAM8 and ADAM9." (PMID 33578644, 2021). "ADAM8, besides cleaving important ECM components of the tumor stroma such as collagen I, fibronectin and periostin, can cluster with β1 integrin and could direct tumor cell invasion through localized proteolytic ECM degradation in protrusions of cancer cells." (PMID 31591367, 2019). "The comparison of soluble ADAM8 in early (T1/2, N0) and advanced (T3/4, N+) tumor stages did also not reveal a significant difference." (PMID 22369429, 2012). "However, these numerous effects of ADAM8 in tumor cells do not rely solely on its extracellular protease function." (PMID 39412616, 2025). "This shows that tumor angiogenesis is also restricted in the lack of ADAM8." (PMID 38317965, 2024). "It remains to be determined if GBM resident immune cells such as macrophages that constitutively express ADAM8 could release EVs that might fail to suppress MMP9 expression in target cells, in conjunction with the possible tumor-promoting role of ADAM8 in macrophages." (PMID 35371977, 2022). "Moreover, survival analysis indicated that CRC patients with ADAM8-positive tumours had worse 5-year overall survival and 5-year disease free survival in comparison with patients with ADAM8-negative tumours." (PMID 35565436, 2022). "Unfortunately, in contrast to tumor expression, serum levels of ADAM8 did not predict survival." (PMID 22369429, 2012). "Furthermore, a panel of highly specific monoclonal antibodies against ADAM8, identified through hybridoma screening, has shown significant anticancer activity in TNBC models, with two lead antibodies, ADP2 and ADP13, reducing tumour growth and metastasis and improving survival in mice." (PMID 40427200, 2025). "However, no information is available on ADAM8 expression in cells of the tumor microenvironment." (PMID 33578644, 2021). "While it is known ADAM8 and EMT play important roles in tumour invasion and metastasis, no prior studies have investigated the correlation between ADAM8 and EMT." (PMID 32954649, 2020). "A profound decrease in the numbers of CTCs was observed with ADAM8 KD (12.8 ± 7.0 versus 0.0 ± 2.0/μl of blood), suggesting that ADAM8 might be involved in dissemination of CTCs; although the possibility that this relates to the large difference in tumor burden could not be excluded." (PMID 24375628, 2014).
cancer (52 papers, 2011 to 2026). A tumor composed of atypical neoplastic, often pleomorphic cells that invade other tissues. "Another top rejuvenation-associated gene, Adam8, encodes a metalloprotease involved in inflammation, tissue remodeling, and cancer progression, further supporting a shared mechanistic axis between rejuvenation, regeneration, and oncogenesis." (PMID 41509418, 2025). "ADAM8 has emerged as a significant player in various cancers, highlighting its potential as both a diagnostic and therapeutic target." (PMID 40427200, 2025). "Consequently, ADAM8 level has been tightly linked to the invasion and metastasis of several malignant cancers and affected the overall outcome of cancer patients’ prognosis." (PMID 36910158, 2023). "As ADAM8 has been implicated in multiple solid malignancies, continued development of this assay may have broad impact on cancer management." (PMID 37568162, 2023). "As ADAM8 has been implicated in multiple solid malignancies, including those of the breast, lung, liver, pancreas, stomach, colon, bone, and head and neck, continued development of a clinical assay may have broad impact on cancer management." (PMID 37568162, 2023). "On the other hand, ADAM8 is increased in a variety of cancer types, correlating with cancer progression, metastasis, chemoresistance, and poor prognosis, and primarily recognized as a cancer biomarker and a therapeutic target." (PMID 40688684, 2025). "ADAM8 has been revealed to play a role in cancer cell invasion through its mediation of the MAPK pathway." (PMID 38218854, 2024). "ADAM8 has also been shown to play multiple roles in cancer cell migration, mechanics, and extracellular matrix remodeling." (PMID 38218854, 2024). "The screening of four top candidates for in vivo anti-cancer activity in an orthotopic MDA-MB-231 TNBC model of ADAM8-driven primary growth identified two lead mAbs, ADP2 and ADP13." (PMID 38675197, 2024). "Here, we report on the isolation of a new class of highly specific human ADAM8 mAbs that bind to sequences within its DI, inhibit both its MP and DI activities, and demonstrate substantial in vivo anti-cancer efficacy." (PMID 38675197, 2024). "Apart from the correlation of ADAM8 expression and the development and malignant progression of cancers, there is also a functional connection revealed." (PMID 36910158, 2023). "When being upregulated in cancer, the proteolytic activity of ADAM8 is capable of fostering tumorigenesis through its ability to trigger angiogenesis and subsequently contribute to metastasis." (PMID 36910158, 2023). "Adam8-shRNA-transfected MDA-MB-231 cells did, however, result in the ablation of myCAF marker expression, indicating that Adam8 expression in cancer cells is required for the MSC development of the myCAF phenotype." (PMID 37370863, 2023). "A member of this family, ADAM8, has gained attention in regulating disorders, such as neurogenerative diseases, immune function and cancer, by attenuating the function of proteins nearby the extracellular membrane leaflet." (PMID 36910158, 2023). "The role of ADAM8 has been increasingly recognized in cancer research, with a focus on malignant progression that involves restructuring the environment of primary tumors." (PMID 36910158, 2023). "Here, the shedding function, direct and indirect matrix degradation, effects on cancer cell mobility and transmigration, and the interplay of ADAM8 with matrix-embedded neighboring cells are presented and discussed." (PMID 36910158, 2023). "In the past, the major focus of research about ADAMs have been on neurogenerative diseases, such as Alzheimer, however, there seems to be evidence for a connection between ADAM8 and cancer." (PMID 36910158, 2023). "Adam8 was then identified as a candidate secreted protein induced by myCAF-mediated cancer stemness." (PMID 37370863, 2023).
cancer (continued). "In a manner similar to that presented for α-SMA, the cancer cell expression of both stemness markers increased with a plateau at 30 h, except in instances wherein Adam8 mAb or lentivirus Adam8 KO were present." (PMID 37370863, 2023). "A high expression rate of ADAM8 is accompanied by an augmented amount of circulating cancer cells and subsequently a higher abundance of brain metastases in orthotopic mouse models." (PMID 36910158, 2023). "In summary, this review presents recent advances in substrates/ligands and functions of ADAM8 in its new role in cancer and its potential link to cell mechanical properties and discusses matrix mechanics modifying properties." (PMID 36910158, 2023). "It was well established that in addition to disintegrating and remodelling ECM, ADAM8 also involved in the activation of integrins through the so‐called ‘integrin‐binding loop’ and led to the migration and invasion of cancer cells." (PMID 32954649, 2020). "The level of ADAM8 was closely related to the invasion and metastasis of various malignant tumours and influenced the prognosis of cancer patients." (PMID 32954649, 2020). "This is consistent with the studies of ADAM8 in tumorigenesis ADAM8 plays a variety of roles to modulate the activities of cancer cells." (PMID 31640732, 2019). "ADAM8 catalyzes the cleavage reaction of the substrate collagen I, contributing to the invasion, migration and metastasis of cancer cells." (PMID 31640732, 2019). "As a member of the A Disintegrin and Metalloproteinase family (ADAM), ADAM8 has been studied extensively in the area of cancer biology." (PMID 31640732, 2019). "A member of the ADAM family, ADAM8 has been detected in many cell types and various types of cancer." (PMID 25098630, 2014). "The observation that WA treatment downregulates mRNA expression of ADAM8 and uPA, and negatively affects uPA protein levels and enzymatic activity, further strengthens the potential therapeutic effect of WA in cancer therapy." (PMID 24498382, 2014). "Mechanistically, ADAM8 is involved in tumorigenesis by stimulating angiogenesis, increasing cellular abilities of invasion and migration, and inhibiting cancer cell apoptosis." (PMID 25098630, 2014). "Additionally, propofol, a common anesthetic, has been studied for its effects on cancer cells, particularly its impact on ADAM8." (PMID 40427200, 2025). "ADAM8 is considered to be an important factor in the development of cancer." (PMID 39329961, 2024). "However, increased ADAM8 expression has been observed in response to inflammatory processes and in different types of cancers." (PMID 38218854, 2024). "Considering that ADAM8 critically promoted proliferation and invasion of cancer cells related to MAPKs signaling, we determined whether ADAM8 promoted neuroinflammatory activities in microglia by directly acting on ERK1/2, JNK1/2 or p38." (PMID 38755530, 2024). "Previously, Awan and colleagues found that ADAM8 plays a crucial role in promoting the proliferation, survival, and migration of hepatocellular carcinoma cells, ultimately leading to metastasis of the cancer." (PMID 38218854, 2024). "Moreover, the most probable mechanical impact of ADAM8 on cancer cells and their matrix environment is addressed and debated." (PMID 36910158, 2023). "Previously, we isolated a panel of monoclonal antibodies, termed ADPs, with high binding activity to human ADAM8, no cross-reactivity to closely related ADAM family members and strong inhibitory activity, for development into an ADAM8-targeted cancer therapy (manuscript in preparation)." (PMID 37568162, 2023). "In view of the high levels of endogenous expression of ADAM8 in macrophages, it has been hypothesized that ADAM8 performs essential functions in the interactions between cancer cells and macrophages." (PMID 36910158, 2023). "For all of these cancers, ADAM8 expression was found to be unfavorable." (PMID 37568162, 2023).
cancer (continued). "The most important question that arises is whether there is a link between ADAM8 and malignant progression of cancer." (PMID 36910158, 2023). "Adam8 was identified as a candidate secreted protein induced by myCAF-mediated cancer stemness." (PMID 37370863, 2023). "A deeper comprehension of the regulatory mechanisms governing the expression, subcellular localization, and activity of ADAM8 is expected to reveal appropriate drug targets that will permit a more tailored and fine-tuned modification of its proteolytic activity in cancer development and metastasis." (PMID 36910158, 2023). "We hypothesize that targeting Adam8 in the extracellular space using RNA aptamer technology can inhibit the growth and metastasis of cancer cells." (PMID 37370863, 2023). "Thus, this review article highlights the various roles of ADAM8 with particular emphasis on pathological conditions, such as cancer and malignant cancer progression." (PMID 36910158, 2023). "The motility of cells, such as cancer cells, has been proposed to be dependent on ADAM8, as it has been explored in transmembrane assays with Porcine Brain Endothelial Cells (PBEC) as a cell monolayer on top of the membrane and primary rat astrocytes in the upper chamber." (PMID 37287457, 2023). "In particular, MMP-9 expression has been found to be increased in ADAM8-positive cancers." (PMID 36910158, 2023). "The focus of this review is on the relationship between ADAM8 and cancer, with particular emphasis on cancer cell mobility, transendothelial migration of cancer cells, epithelial-to-mesenchymal transition (EMT), and malignant cancer progression such as metastasis." (PMID 36910158, 2023). "The ADAM8 Disintegrin (DI) domain mediated TNBC cell adhesion to endothelial cells via activation of integrins on the cancer cell surface that permits intravasation through the blood vessel wall into the blood stream as well as extravasation at distant sites to establish metastases." (PMID 37568162, 2023). "In the following, the focus is on the function of ADAM8 in cancer and its malignant progression." (PMID 36910158, 2023). "Beyond ADAM8’s function in cancer, it is coupled inflammation, which may also play a role in advancement of cancer." (PMID 36910158, 2023). "ADAM8, 19, and 28 showed a significantly positive correlation with both the immune score and stromal score in pan-cancers, indicating that these genes may play an important role in TME development and could be potential immunotherapy targets." (PMID 37082201, 2023). "While research publications have employed various commercial IHC antibodies to evaluate ADAM8 levels in cancer, these antibodies cannot be used in the clinic due to their lack of characterization (i.e., studies on target specificity, linearity and range of detection)." (PMID 37568162, 2023). "In addition, the markedly increased ADAM8 in a variety of malignant tumors has also attracted attention to its role in the malignant behavior of tumors." (PMID 36230833, 2022). "The authors concluded that ADAM8 is overexpressed in PC tissue and may promote cancer cell invasiveness as well as correlate with reduced PC survival." (PMID 35565436, 2022). "The metalloproteinase ADAM8 is a proteolytically active member of this family, which is upregulated in several cancers and inflammatory diseases, where ADAM8 can act as a protease cleaving surface molecules and as an adhesion molecules to promote cell migration." (PMID 33814981, 2021). "These preliminary results provedthe efficacy of bifunctional inhibitors in cancer cells overexpressingADAM8, but further studies will be needed to improve the selectivityof compound 2 for ADAM8 over ADAM17 and to ultimatelydefine its mechanism of action at a molecular level." (PMID 35111280, 2021). "Furthermore, the mRNA level of ADAM8 at cancer tissues was significantly higher than that of adjacent normal tissues (1.54 ± 0.17 vs 0.94 ± 0.08, respectively; P = .0012)." (PMID 32954649, 2020).
cancer (continued). "Because WA predominantly increased DNA methylation, we mainly focused on verification of hypermethylation effects obtained for selected genes related to cancer invasiveness (ADAM8, PLAU, and TNFSF12), detoxification (GSTM1) or mitochondrial functions (ME3), in relation to gene expression silencing." (PMID 28467815, 2017). "Interestingly, ADAM8 expression was detected under several pathological conditions characterized by inflammation and extracellular matrix remodeling, including cancer." (PMID 24375628, 2014). "Notably, high ADAM8 expression has been detected in a variety of solid tumors in addition to breast, including colon, stomach, liver, pancreas, lung, head and neck, and bone, and in each cancer correlates with a poor outcome." (PMID 38675197, 2024). "However, for a long time not much was known about the interplay between ADAM8 and EMT, although it has been hypothesized that ADAM8 is critical for cancer invasion and metastasis." (PMID 36910158, 2023). "Moreover, Transwell assay was used to evaluate the effect of ADAM8 on the invasion of cancer cells." (PMID 32954649, 2020). "Specifically, ADAM8 and ADAM12 consistently exhibited a significant upregulation trend in most cancer types." (PMID 39346916, 2024). "First and foremost it has been established that the substantial functioning of ADAM8 lies in the extracellular liberation of MMP-9 and LCN2, which are two key facilitators of cancer advancement in PDAC." (PMID 36910158, 2023). "However, the mechanism by which Adam8 abets cancer potentiation is unknown." (PMID 37370863, 2023). "In the results of the current series of RNAseq analyses, Adam8, CA12, and CDH6 were identified as candidates for myCAF-induced cancer-stemness-related genes with secreted proteins." (PMID 37370863, 2023). "First, we demonstrate the essential function of ADAM8 in the extracellular release of MMP-9 and LCN2, two important mediators of cancer progression in PDAC." (PMID 35216088, 2022). "The active form of ADAM8 cleaved important ECM components and contributed to the invasiveness of cancer cells." (PMID 36231102, 2022). "The ADAM (a disintegrin and metalloproteinases) family members, including ADAM8, ADAM9, ADAM10, ADAM12 and ADAM15, exert their action by degrading the ECM proteins collagen IV and FN, thus contributing to niche formation and cancer progression." (PMID 31591367, 2019). "Using ADAM8 knockdown strategies, 68 miRNAs were identified in MDA-MB-231 TNBC cells, including miR-720 which is overexpressed in several cancers and secreted from TNBC cells." (PMID 27039296, 2016). "In summary, our results show that ADAM8 is overexpressed in CRC tissues, promoting cancer cell proliferation, inducing cell apoptosis and correlating with worse OS and DFS." (PMID 25098630, 2014). "The overexpression of ADAM8, ADAM9, ADAM10, ADAM12, ADAM15, ADAM17, and ADAM28 are reported from various cancers." (PMID 22272227, 2012). "Additionally, ADAM8 cleaves extracellular matrix (ECM) components such as collagen I, fibronectin, and periostin, which are important elements of the cancer stroma." (PMID 40427200, 2025). "Furthermore, an influence of ADAM8 expression on MAPK and AKT signaling has also been observed in other cancers, underscoring our current findings in MM." (PMID 39261477, 2024). "To date, there has been no successful targeted treatment against ADAM8-expressing cancers either marketed or, to our knowledge, in the pipeline." (PMID 38675197, 2024). "In general, the importance of ADAM8 in cancer progression is misjudged and it has not been subject of many cancer studies, although it has the power to act as a key molecule in various timepoints in cancer evolution and its malignant progression." (PMID 36910158, 2023). "In contrast to other family members like ADAM17 and ADAM10, ADAM8 is non-essential in physiological states but has been upregulated in inflammatory processes and various cancers." (PMID 36910158, 2023).